PIK3CA (phosphatidylinositol-4,5-bisphosphate 3-kinase catalytic subunit alpha)
Diseases named in the same sentence as PIK3CA in open-access papers (continued):
Sharing a sentence is not in itself a finding about the gene and the disease.
gastric cancer (continued). "Because of their relatively large sample sizes, including this study that included samples from over 200 samples, these findings, taken together, confirm the lack of relationship between PIK3CA mutations and prognosis in gastric cancer patients." (PMID 27388016, 2016). "Upregulation of PIK3CA expression is likely related to lymph node metastasis in gastric cancer." (PMID 25003395, 2014). "Taken together, PIK3CA amplification may be served as a potential prognostic marker for gastric cancer patients." (PMID 22292935, 2012). "Multivariate Cox regression analysis indicated that PIK3CA amplification is a predictor of poor prognosis for gastric cancer patients (HR = 2.59, 95% CI = 1.39-4.82, P = 0.003) as an independently variable with respect to age, differentiation, lymph node metastasis, and TNM stage." (PMID 22292935, 2012). "Most noteworthy, PIK3CA amplification significantly affected the overall prognosis in gastric cancer whatever the patients who had early-stage or late-stage tumors, suggesting that this genetic event plays an important role in the multistep process of gastric carcinogenesis." (PMID 22292935, 2012). "Instead, our study demonstrated PIK3CA gene was highly amplified in gastric cancer." (PMID 22292935, 2012). "The overall survival of gastric cancer patients with and without PIK3CA mutations/amplification was compared using the log-rank test." (PMID 22292935, 2012). "We analysed the sequences of exons 9 and 20 of the PIK3CA gene in 264 advanced gastric cancers." (PMID 20398348, 2010). "The lack of associations suggests that alteration of PIK3CA is an event that occurs early in a subset of gastric cancers that progresses towards malignancy through other mechanisms." (PMID 20398348, 2010). "We noted a higher tendency of high-level MSI in gastric cancers with PIK3CA mutations (3 in 4, 75%) than in those without (18 in 90, 20%)." (PMID 15784156, 2005). "Although the mechanisms of how EBV infection leads to EBV-associated gastric cancer are still unclear, it is proposed that EBV-positive gastric cancers cause some gene amplifications, leading to carcinogenesis through various molecular pathways, especially PIK3CA." (PMID 40575380, 2025). "Similarly, PIK3CA p.H1047R was shared among colorectal, breast, and gastric cancers." (PMID 39748775, 2025). "Re-analysis of the generated WES data within the SOLVE-RD consortium revealed one ClinVar-reported missense variant in PIK3CA (NM_006218.4; c.3140A>G; p.(His1047Arg)), a gene associated with somatic overgrowth syndromes, but not previously associated with gastric cancer." (PMID 34075207, 2021). "Similarly, PIK3CA amplifications were associated with the occurrence of diffuse-type and poorly differentiated gastric cancers and peritoneal recurrence as compared to those without PIK3CA amplifications." (PMID 31905960, 2019). "However, overall survival and disease-free survival were similar in patients with and without PIK3CA mutations, indicating that PIK3CA mutations do not affect mortality after resection of gastric cancer." (PMID 27388016, 2016). "Therefore, whether PIK3CA amplifications can serve as a prognostic indicator for gastric cancers remains unclear." (PMID 26701847, 2016). "In summary, our data showed that PIK3CA mutations may not be frequent genetic event in gastric cancer, however, PIK3CA gene was highly amplified in gastric cancer." (PMID 22292935, 2012). "However, PIK3CA amplification significantly affected clinical outcomes of gastric cancer patients." (PMID 22292935, 2012). "PIK3CA mutations did not affect the overall prognosis of gastric cancer patients (P = 0.44)." (PMID 22292935, 2012). "However, our study showed that the most common activating PIK3CA mutations reported in other cancers were not frequent in gastric cancer." (PMID 22292935, 2012).
gastric cancer (continued). "However, until this work, there was no sound investigation on the association of PIK3CA mutations and amplification with clinical outcome in gastric cancer, particularly the latter." (PMID 22292935, 2012). "Some of the PIK3CA mutations were detected in the early lesions of breast cancer carcinoma, hepatocellular carcinoma, and gastric carcinomas, suggesting that PIK3CA mutation may occur independent of stage of the tumors." (PMID 19384426, 2007). "Through network analysis, AKT1, MAPK1, CDK2, PIK3CA, and VEGFA were found to be the key targets of HDW in the treatment of gastric cancer." (PMID 39086391, 2024). "LOXL1-AS1 is also linked with downregulation of miR-142–5p and upregulation of PIK3CA, suggesting a LOXL1-AS1/miR-142–5p/PIK3CA axis in the progression and development of gastric cancer." (PMID 39136001, 2024). "For example, the CNV amplification of PIK3CA enhanced PI3-kinase activity and elevated phosphorylated Akt level, leading aberrant cell proliferation and poor prognosis in gastric cancer." (PMID 38346070, 2024). "Similar results were obtained in EBV-uninfected PIK3CA mutant HGC-27 gastric carcinoma and in PIK3CA wildtype SNU-1 gastric carcinoma cells." (PMID 38746323, 2024). "Others have been reported to have good potential to be prognostic biomarkers for CRC (CDKN1A, CDKN1B), stomach cancer (MMP2,) and esophageal cancer (EGFR, PIK3CA,)." (PMID 35681633, 2022). "SNPs of PIK3CA (p.Glu707Lys) and KDR (p.Gln472His) were more frequent in gastric cancer patients than in healthy Japanese people (p < 2.2 × 10–16 and p = 0.001, respectively; Bonferroni-corrected significance level = 0.003)." (PMID 34873204, 2021). "On the other hand, PIK3CA exhibits divergence in some tumor contexts such as stomach cancer and bladder cancer but not in most others, suggesting that recurrent PIK3CA mutations may result in unique downstream transcriptional signals depending on the unique cancer context in which they developed." (PMID 33957863, 2021). "Among the 90 gastric cancers, 10 cancers had gene amplification of one of ERBB2, KRAS, PIK3CA, and MET." (PMID 34873204, 2021). "ERBB2 was most frequently amplified (6 of the 90 gastric cancers, 7%), and KRAS (2 cancers, 2%), PIK3CA (1 cancer, 1%), and MET (1 cancer, 1%) followed." (PMID 34873204, 2021). "Researches demonstrated that PIK3CA, PIK3CB, AKT1 and mTOR are overexpressed in GC cell lines, and mTOR pathway is active in almost 60% of gastric cancer patients." (PMID 30754640, 2019). "PIK3CA was also shown to be a direct target of miR-203, whose downregulation was found to increase AKT signaling in gastric cancer." (PMID 27935861, 2017). "To investigate the effect of PIK3CA amplification on the activity of PI3K/Akt signaling pathway, we randomly selected 13 gastric cancer samples with various PIK3CA copies and did immunohistostaining for p-Akt." (PMID 22292935, 2012). "Gene PIK3CA was detected based on GCPan and GGCPan but not on GRCh38, and it was reported as a gastric cancer driver gene in TCGA-STAD and Stomach-AdenoCA cohorts." (PMID 39870503, 2025).
gastric cancer (continued). "Otherwise, the downregulation of PIK3CA, a well-known oncogene, was also observed in MGC-803 cells with NDUFC1 knockdown and supposed to participate in the NDUFC1 induced regulation of gastric cancer." (PMID 34966665, 2021). "It was known that mutations in genes such as CDH1, PIK3CA, ARID1A (AT-rich interactive domain 1A), EGFR, and PTEN existed in gastric cancer, providing potential circulating DNA for detection of gastric cancer." (PMID 33693004, 2021). "VGLL1 is a prognostic biomarker that correlates with PIK3CA and PIK3CB in gastric cancer." (PMID 31816819, 2019). "Gastric cancer patients with PIK3CA amplifications had more diffuse-type and poorly differentiated gastric cancer and more peritoneal recurrences compared with patients without PIK3CA amplifications." (PMID 26701847, 2016). "Furthermore, CagA participates in cell signaling by activating the PIK3CA and KRAS pathways, ERK (MAPK), and MEK/ERK and JAK1 signaling pathway in gastric cancer cells." (PMID 23431236, 2013). "With a gene copy number of 4 or more defined as amplification, we found the incidence of PIK3CA amplification in gastric cancers was 67% (88/131) in the present study, whereas no PIK3CA amplification was found in the 37 normal controls." (PMID 22292935, 2012). "This study evidences previously observed perturbations of the KRAS, ERBB2, EGFR, MET, PIK3CA, FGFR2 and AURKA genes in gastric cancer and suggests some of the targeted therapies approved or in clinical development would be of benefit to 11 of the 50 patients studied." (PMID 21781349, 2011). "Data extracted from microarray studies showed an increased expression of PIK3CA in gastric cancers when compared with the non-neoplastic gastric mucosae (p < 0.001)." (PMID 15784156, 2005). "We have confirmed that expression level of PIK3CA was significantly higher in gastric cancers (n = 87, mean = 0.099, SD = 0.428) when compared with non-neoplastic gastric mucosae (n = 22, mean = -0.418, SD = 0.426; Student's t-Test, p < 0.001)." (PMID 15784156, 2005). "Overexpression of PIK3CA and consequent Akt activation is also common among gastric malignancies; thus, constituents of the PI3K/Akt pathway may serve as therapeutic targets for the treatment of gastric cancer." (PMID 38791602, 2024). "Regarding PIK3CA amplifications in gastric cancer, our results showed that patients with PIK3CA amplifications were more likely to have diffuse-type, poorly differentiated gastric cancer and peritoneal seeding compared with patients without PIK3CA amplifications." (PMID 26701847, 2016). "Results showed that expression levels of NKX6.3, CDH1, CDKN1A, and EP300 were decreased while expression levels of NFκB p65, AICDA, CBFβ, APOBEC3A, APOBEC3B, RhoA, ROCK1, ROCK2, PIK3CA, and CCND1 were increased in CagA positive gastric cancers compared to those in CagA negative cases." (PMID 30514953, 2018).
cervical carcinoma (169 papers, 2003 to 2026). A carcinoma arising from either the exocervical squamous epithelium or the endocervical glandular epithelium. "In plasma ctDNA samples collected prior to treatment from 177 patients with invasive cervical cancer, two PIK3CA mutations (p.E545K and p.E542K) were identified." (PMID 41602395, 2026). "The results indicated that PIK3CA was the most commonly mutated gene in cervical cancer (approximately 30%), consistent with the detection results of PIK3CA in cervical cancer tissue." (PMID 41602395, 2026). "PIK3CA mutations were found most in cervical cancer patients, and more than 25% of patients had a high tumor mutational burden." (PMID 41502526, 2025). "The most significant tumor reduction of −65%, with the response still ongoing for more than a year after the data cut-off, was observed in a cervical cancer patient with ErbB2 overexpression and additional PIK3CA, AKT, and mTOR mutations." (PMID 39908697, 2025). "PIK3CA (phosphatidylinositol-4,5-bisphosphate 3-kinase catalytic subunit alpha) mutations are commonly seen in breast and cervical cancers." (PMID 39684787, 2024). "PIK3CA was the most frequently mutated SMGs in cervical cancer, as revealed by both RNA-seq and DNA-seq analyses (RNA-seq: 21% of all available CESCs; DNA-seq: 28%)." (PMID 38783092, 2024). "A phase II clinical trial is currently underway to evaluate the efficacy of combining Trametinib and AKT inhibitor GSK21411795 for the treatment of recurrent cervical cancer with PIK3CA and KRAS mutation." (PMID 38356704, 2024). "The Cancer Genome Atlas (TCGA) database indicates high frequencies of PIK3CA mutations and copy number amplifications in cervical cancer patients, making PIK3CA a promising therapeutic target." (PMID 39590348, 2024). "Prior studies have demonstrated that the presence of the PIK3CA-E545K mutation confers radiation resistance in cervical cancer, thus indicating an unfavorable prognosis for patients with activated PIK3 signaling." (PMID 38651153, 2024). "In cervical cancer, 6 out of 124 cases (4.62%) with multiple PIK3CA mutations exhibited PTEN mutations compared with 3 out of 42 cases (7.14%) with a single mutation." (PMID 39054873, 2024). "Approximately 40% of cervical cancer cases exhibit mutations or amplifications in PIK3CA, which is the most prevalent genetic aberration observed in this type of cancer." (PMID 38651153, 2024). "The strong support from both miRWALK and TargetScan for some miRNAs linked to PIK3CA emphasizes their importance in cancer biology, particularly in breast and cervical cancers, where PIK3CA mutations are prevalent." (PMID 39684787, 2024). "The landmark studies by the Cancer Genome Atlas (TCGA) have reported that the most frequent mutations in cervical cancer are PIK3CA (26%), EP300 (11%), FBXW7 (11%), and PTEN (8%)." (PMID 37256181, 2023). "Mutations in PIK3CA affect glucose metabolism and proliferation in cervical cancer by activating the AKT/glycogen synthase kinase 3β/β-catenin signalling pathway, thereby reversing resistance to radiotherapy." (PMID 37884919, 2023). "The PIK3CA gene has been reported to be frequently mutated in patients with cervical cancer in the United States of America." (PMID 37884919, 2023). "In cervical cancer patients with PIK3CA mutations, approximately 60% contain the E545K substitution, a mutation associated with an enhanced migratory phenotype in cervical cancer cells." (PMID 36763589, 2023). "A previous case-control study in the Philippines showed that the PIK3CA gene was found mutated in 10.71 % of cervical cancer patients." (PMID 35795639, 2022). "PIK3CA is the second most frequently mutated oncogene across cancers, comprising 39% of mutations found in cervical cancer." (PMID 36354662, 2022).
cervical carcinoma (continued). "PIK3CA gene activation mutations are presented in a variety of malignancies, such as lymphoma, breast, head and neck colorectal, and cervical cancer." (PMID 36567775, 2022). "More research is needed to determine alpelisib’s role in terms of efficacy and safety in PIK3CA-mutated advanced/recurrent cervical cancer." (PMID 35448205, 2022). "We thought that variant TTN and PIK3CA was the driving factor of the tumorigenesis of cervical cancer." (PMID 35935576, 2022). "Another study showed that PIK3CA mutations were associated with the response to immunotherapy in cervical cancer." (PMID 36333792, 2022). "Frequently mutated genes in cervical cancer included the PIK3CA, KMT2D, and KMT2C genes, among others." (PMID 36333792, 2022). "Two PIK3CA mutations, p.E542K and p.E545K, were measured in cfDNA in pre-treatment plasma of 177 patients with primary invasive cervical cancer." (PMID 35725812, 2022). "Previous studies revealed PIK3CA mutation is frequent in cervical cancer, and is associated with a poor OS and PFS." (PMID 35205332, 2022). "In the recent secondary analysis of the CLAP trial, the PIK3CA mutation was found to be a novel predictive biomarker in cervical cancer patients treated with combination therapy of PD-1 and VEGF-R inhibitor." (PMID 35043008, 2022). "BUL719 (alpelisib) was used in the treatment of PIK3CA-mutated advanced/recurrent cervical cancer where at least two lines of therapy have failed, in a small study from Istituto Nazionale dei Tumori (Milano, Italy)." (PMID 35448205, 2022). "Using targeted sequencing, genomic alterations, such as PIK3CA, linked to molecular-targeting drugs were detected in locally advanced cervical cancer in both our cohort and TCGA dataset." (PMID 34584128, 2021). "Several studies have reported that cervical cancer patients with PIK3CA mutations are associated with worse prognosis than those without the mutation." (PMID 34584128, 2021). "Although these aspects seem to influence the treatment response and survival of cervical cancer patients, the predictive value of PIK3CA mutations remains inconclusive." (PMID 34830902, 2021). "PIK3CA mutations are the most frequent actionable mutations in cervical cancers and have been approved by the US Food and Drug Administration (FDA) as a predictive biomarker for the use of the PI3K inhibitor, alpelisib." (PMID 33802174, 2021). "The most frequent significantly mutated genes (SMGs) across the 430 cervical carcinomas were previously reported and included PIK3CA (27%), KMT2C (also known as MLL3) (19%), KMT2D (also known as MLL2) (13%), EP300 (12%), FBXW7 (12%), FAT1 (8%), and PTEN (8%)." (PMID 34620846, 2021). "EGFR, KRAS and PIK3CA genes were selected to be amplified in specific regions since these genes are implicated in most cancers, especially in cervical cancers." (PMID 33736612, 2021). "In cervical cancer, PIK3CA mutation and increased expression of pAKT have been found to be related with resistance to radiotherapy." (PMID 34737943, 2021). "Inhibiting β-catenin enhances radiosensitivity of cervical cancer cells in vitro and in vivo particularly in PIK3CA-E545K mutated cells." (PMID 34737943, 2021). "The Wnt/β catenin pathway also presents an increased number of mutations in key component genes in PIK3CA mutated cervical cancers compared with PIK3CA wild-type counterparts." (PMID 33435133, 2021). "Our study found that the FSCN1 gene is related to radiosensitivity and is associated with therapeutic efficacy and prognosis in cervical cancer and head and neck cancer patients with PIK3CA alterations." (PMID 34249689, 2021). "In contrast, another study detected PIK3CA mutations in 37.3% of 161 pre-treatment specimens from cervical cancer patients treated with CRT, which was associated with worse OS in univariate analysis (p = 0.037)." (PMID 34830902, 2021).